SMURF2 (SMAD specific E3 ubiquitin protein ligase 2)
Diseases named in the same sentence as SMURF2 in open-access papers (continued):
Sharing a sentence is not in itself a finding about the gene and the disease.
cancer (continued). "These discrepancies could be explained by different types of cancer cell models used in these studies: HeLa vs. U2OS cells, implying that biological effects of Smurf2 should be very carefully interpreted taking into account cellular context, genetic make-up, and experimental settings." (PMID 30116722, 2018). "Similarly, when PR was no/mild, 66.13 and 58.06% of malignant tumors showed moderate/intense expression of Smurf2 and CNKSR2." (PMID 29534682, 2018). "Interestingly, we observed a statistically significant association between Smurf2 and CNKSR2 expression with the ER, PR, and HER2 status of non-malignant and malignant tumors." (PMID 29534682, 2018). "It has been hypothesized that the pleotropic substrate repertoire of SMURF2, including its interactors and targets which have not yet been identified, and the differential access of SMURF2 to its interactors in normal and cancer cells are related to its duality." (PMID 31003445, 2019). "Among genes that are not listed as cancer genes in “Cancer gene census” it is worth mentioning GRHL2 and SMURF2." (PMID 39208653, 2024). "No marked alterations of SMURF2 mRNA levels were found among grades II, III, and IV cancer or among classical, mesenchymal, and proneural tumors, according to the Cancer Genome Atlas (TCGA)." (PMID 35017630, 2022). "Besides that, some affected new potential cancer drivers (genes that were not cataloged at CGC) were identified, such as CACNA1E, GRHL2, MTHFD2, PIK3AP1, RSBN1, SEMA6D, and SMURF2." (PMID 39208653, 2024). "Interestingly, while acting in cancer cells as a KAP1 stabilizing factor, in untransformed IMR90 and BJ1 cells, SMURF2 showed a negative impact on KAP1 expression, the phenomenon that was also observed in certain Smurf2KO tissues." (PMID 35406379, 2022). "The data show that despite the heterogeneous expression of SMURF2 in different BRCA strains, SMURF2 has a higher cytoplasmic/nuclear ratio in cancer cells in comparison to the non-tumorigenic MCF10A cell model, supporting our findings obtained in clinical tissue samples." (PMID 31003445, 2019). "We next observed that the expression levels of Smurf2 and CNKSR2 in relation with the hormonal (ER and PR) and HER2 status of breast tissue samples showed a statistically significant difference among non-malignant and malignant tumors." (PMID 29534682, 2018). "We reported previously that Smurf2 knockdown significantly downregulated the CNKSR2 protein levels in MDA-MB-231, MCF-7, SW480, and SCC131 cancer cell lines without any effect on CNKSR2 mRNA, suggesting that Smurf2 controls the CNKSR2 protein level possibly through proteolytic regulation." (PMID 29534682, 2018). "Contrarily, we observed that when HER2 was no/mild, only 40.32 and 38.71% of malignant tumors showed moderate/intense expression of Smurf2 and CNKSR2 whereas 50.00 and 48.39% of malignant tumors showed moderate/intense expression of Smurf2 and CNKSR2 when HER2 was moderate/intense." (PMID 29534682, 2018). "Interestingly, both the SMURF2 and LMNA genes are not frequently altered in human malignancies; however, changes in the expression of these genes are common in many cancers." (PMID 29405587, 2018). "In addition, SMURF2 mRNA, but not WNT11 mRNA, is often up-regulated in basal cancers." (PMID 36675340, 2023).
infection (5 papers, 2020 to 2025). The state of being infected such as from the introduction of a foreign agent such as serum, vaccine, antigenic substance or organism. "Infection efficiency was evaluated using green fluorescent proteins in A549 and H460 cells cells and then three shRNAs against SMURF2 in A549 and H460 cells were confirmed by WB." (PMID 37497010, 2023). "Infection was also inhibited by SMURF2 knockdown, although to a lesser extent than the SIAH1 knockdown or miR-424 expression." (PMID 32117091, 2020). "We speculate that it would be beneficial for VP40 to interact with additional HECT family E3 ligases, like SMURF2, that are present in relatively high abundance during infection of those epithelial or endothelial cell types." (PMID 33673144, 2021). "Like SIAH1, miR-424 inhibited expression of SMURF1 and SMURF2 during DENV2 infection." (PMID 32117091, 2020). "SMURF1 and SMURF2 transcripts were detectable prior to infection and showed moderate induction during DENV2 infection, although SMURF1 expression dropped to near constitutive levels by 48 h." (PMID 32117091, 2020). "In both HL-60 and K562 cells, shSmurf2 infection decreased the expression of Smurf2 but did not alter CASC3 mRNA levels." (PMID 40978141, 2025).
inflammation (2 papers, 2016 to 2021). Aberrant reaction of the microcirculation characterized by movement of fluid and leukocytes from the blood into extravascular tissues. "We then tested a hypothesis that the protection of Smad3 KO‐db/db mice from cardiac inflammation may be associated with the inactivation of NF‐κB signalling by blocking Smurf2‐mediated ubiquitin degradation of cardiac Smad7." (PMID 33733577, 2021).
cardiovascular diseases (1 paper, 2020). "We will also perform future experiments in Smurf2 knockout mice to explore the role of Smurf2 in cardiovascular diseases." (PMID 32167680, 2020). "Our research provides a new therapeutic target for the treatment of cardiovascular diseases, and Smurf2 targeting may be a new method of action in response to vascular endothelial cell injury." (PMID 32167680, 2020).
heart diseases (1 paper, 2020). "Among the nine members of the NEDD4 family, NEDD4-1, NEDD4L, ITCH, WWP1, WWP2, SMURF1 and SMURF2 are involved in heart diseases." (PMID 33110392, 2020).
neurodegenerative disease (1 paper, 2013). A disorder of the central nervous system characterized by gradual and progressive loss of neural tissue and neurologic function. "Together, our results support Smurf2 as a regulator of EZH2 turnover to facilitate PPARγ expression, which is specifically required for neuron differentiation, providing a molecular mechanism for clinical applications in the neurodegenerative diseases." (PMID 23526793, 2013).
SMURF2 also shares sentences with these, for which no sentence is quoted: cervical carcinoma (4 papers); atrial fibrillation (2); breast adenocarcinoma (2); esophageal squamous cell carcinoma (2); myocardial infarction (2); virus infection (2); acute myeloid leukemia (1); adenocarcinoma (1); anaplastic astrocytoma (1); aortic valve calcification (1); cerebral atherosclerosis (1); Cirrhosis (1); coronary atherosclerosis (1); depression (1); diabetic cardiomyopathy (1); diabetic retinopathy (1); diffuse astrocytoma (1); endometriosis (1); esophageal cancer (1); experimental autoimmune encephalomyelitis (1); gastric cancer (1); head and neck tumours (1); Hutchinson-Gilford progeria syndrome (1); Hypertension (1); hypertensive nephropathy (1); idiopathic dilated cardiomyopathies (1); Infertility (1); invasive breast carcinoma (1); keloid (1); kidney disease (1).
A further 19 diseases each share a sentence with SMURF2 in 1 paper.